WHAMMP3 (WHAMM pseudogene 3)
Synonyms: formerly WHDC1L1; WHAMML1
Gene: Transcribed unprocessed pseudogene on chromosome 15 (22,664,359 to 22,681,605, forward strand). Ensembl gene ENSG00000276141.
Diseases named in the same sentence as WHAMMP3 in open-access papers:
WHAMMP3 is named in the same sentence as 4 diseases in open-access papers, as found by Europe PMC text mining. Sharing a sentence is not in itself a finding about the gene and the disease. The quoted sentences say what the papers report.
Delusion (1 paper, 2021). A delusion is a fixed false belief held despite evidence to the contrary. "Furthermore, six autoantibodies were associated with specific psychopathology symptoms: anti-AP3B2 (persecutory delusions), anti-TDO2 (hallucinations), anti-CRYGN (initial insomnia); anti-APMAP (poor appetite), anti-OLFM1 (above-median cognitive function), and anti-WHAMMP3 (anhedonia and dysphoria)." (PMID 34518517, 2021).
WHAMMP3 also shares sentences with these, for which no sentence is quoted: dysphoria (1 paper); Hallucinations (1); insomnia (1).